IL6 (interleukin 6)
Diseases named in the same sentence as IL6 in open-access papers (continued):
Sharing a sentence is not in itself a finding about the gene and the disease.
colitis (continued). "In addition to these effects, RES administration suppressed the expressions of MCP-1, cytokine-induced neutrophil chemoattractant 1 (CINC-1), TNF-α, IL-1β, IL-6 and IL-12 in rats with TNBS-induced colitis." (PMID 32722619, 2020). "Therefore, the activation of IL-6/JAK2/STAT3 pathway is closely related to inhibit the occurrence and development of colitis, which is consistent with the expected results." (PMID 32081954, 2020). "The first reports showed that A2BARs activation on intestinal epithelial cells increases IL-6 production, resulting in increased neutrophil activation, and upregulation of A2BAR expression has been observed in epithelial cells from mouse or human colitis." (PMID 32971792, 2020). "It was reported that activation of A2BR on intestinal epithelial cells could augment IL-6 production and increased neutrophil activation combined with increased detection of A2BR in epithelial cells isolated from the mouse or human colitis." (PMID 32714089, 2020). "Cytokines IL-1β, IL-6, and TNF-α can activate NF-κB phosphorylation in colitis." (PMID 33664740, 2020). "n‐3 polyunsaturated fatty acids attenuate induced colitis by reducing inducible nitric oxide synthase (iNOS), cyclooxygenase‐2 (COX‐2), IL‐6, and LTB4 as well as regulating tight junction proteins (occludin, claudin‐1) and colonic mRNA levels of trefoil factor 3 (TFF3) and mucin 2 (MUC2)." (PMID 32410383, 2020). "The levels of colonic IL-6 and TNF-α also decreased in Safranal-treated colitis mice." (PMID 31736758, 2019). "Previous reports showed that in an animal model of colitis, mice treated with CTX present an up regulation of local anti-inflammatory cytokines, such as TGF-β and IL-10, and a decreased expression of proinflammatory cytokines, such as IL-6 and TNF-α." (PMID 31757011, 2019). "Next, to confirm the anti-inflammatory effect of SIF on the increased DSS-induced colitis model, we investigated the mRNA expression levels of inflammatory cytokines such as TNF-α, IL-1β, IL-6, MCP1 and inflammatory enzymes iNOS and COX-2 in colon tissues assessed by quantitative RT-PCR." (PMID 31362418, 2019). "The data showed that the induction of colitis using TNBS induced an increase in the expression of pro-inflammatory genes such as Tnf-α, Inf-γ, Il-1β, and Il-6 and, on the other hand, a reduction in the expression of anti-inflammatory cytokines such as Il-10 and Tgf-β." (PMID 30717413, 2019). "In addition, ALA significantly reduced the expression of pro-inflammatory genes, the activity of MPO, and the production of TNF-α, IL-6, NO and PGE2 in DSS colitis mice." (PMID 31719637, 2019). "Particularly, S1PR1 signaling promoted IL-6 production in a STAT3-dependent feedback loop, where IL-6 induced S1PR1 expression in mouse macrophages in vitro, in a model of sickle cell disease, and in dextran sodium sulfate (DSS)-induced colitis." (PMID 31379883, 2019). "However, after treatment with SASP and IN, the levels of IL-6, IL-8, and TNF-α decreased greatly compared with the colitis group, while the levels of IL-10 increased." (PMID 31726738, 2019). "Similarly, the peritoneal macrophages recovered from the rBmaCys-treated colitis mice were alternatively activated and displayed reduced expression of TNF-α and IL-6." (PMID 31683524, 2019). "In our study, we found that thalidomide treatment in modeling or after modeling could reduce the overexpression of Th cell (Th1 and Th17) cytokines including IFN-γ, IGF-1, IL-6, IL-17 and TNF-α in serum and intestinal tissues in TNBS-induced colitis model." (PMID 31920668, 2019). "Our findings revealed that EEP suppressed protein expression levels of inducible pro-inflammatory enzymes (COX-2 and iNOS) and mRNA expression levels of cytokines (IL-6, IL-1β, and TNF-α) due to inhibitory effects of EEP on phosphorylation of NF-κB and STAT3 in DSS-induced colitis mice." (PMID 30621304, 2019).
colitis (continued). "However, at day 7 exacerbated expression of Il6 and Il1β was observed in the colon correlating to the increase in histological injury in the NikΔIE mice, suggesting that pro-inflammatory mediators are not the early causative mechanism for colitis in NikΔIE mice." (PMID 30737385, 2019). "However, administration of JGT to colitis-induced rats significantly decreased levels TNF-α and IL-6, indicating reduced inflammation." (PMID 30800169, 2019). "The IL-6 level was significantly lower in the TMSC and TMSC-CM-conc groups (p = 0.0103, ANOVA), and the IL-17 level was significantly lower in the TMSC-CM and TMSC-CM-conc groups (p = 0.0456, ANOVA) than in the colitis control group." (PMID 31790467, 2019). "Additionally, activation of PXR suppresses the expression of NF-κB target genes including iNOS, IL-1α, IL-1β, IL-6 and TNF-α in the colon of DSS colitis mice." (PMID 31719637, 2019). "In contrast, UroA/UAS03 did not block LPS-induced IL-6 production in AhR−/− macrophages up to 30 μM as well as in AhR−/− mice in TNBS-induced colitis model suggesting that UroA/UAS03 mediate anti-inflammatory activities through AhR-dependent manner." (PMID 30626868, 2019). "Patients who developed ipilimumab-induced colitis had significantly higher numbers of CD4+ T-cells but lower levels of IL-6, IL-8, and sCD25 at baseline compared to those without colitis." (PMID 30887236, 2019). "IL-6, along with other differentially upregulated genes in colitis tissue from patients, was not significantly upregulated in responding tumors." (PMID 31730012, 2019). "For example, SCFAs enemas did not prevent or reduce intestinal damage in TNBS-induced colitis in rats, while butyrate reduced colonic mucosal damage and serum inflammatory cytokines (IL-6, TNF-α, and IL-1β) in DSS-treated mice." (PMID 30915065, 2019). "In addition, M2b macrophage exosomes increased the percentage of Treg cells in mice with DSS-induced colitis and reduced pro-inflammatory cytokine (IL-1β, IL-6, and IL-17A) production in the colon of mice with DSS-induced colitis." (PMID 31749791, 2019). "The anti-inflammatory effects of KA were consistent with the effects on pro-inflammatory mediators, i.e., NO, PGE2, IL-6, and TNF-α, in LPS-induced macrophages; they are known to be involved in the regulation of immune reactions, inflammation, and, in some cases, colitis and death." (PMID 31569788, 2019). "Therefore, both the circulating and colonic cell medium levels of IL-6 and TNF-α were higher in pAdipoR1 mice than in WT mice after acute colitis." (PMID 29540173, 2018). "Importantly our results demonstrated that MCC950 treatment significantly reduced IL-1β, IL-1α, IL17, IL6, IFN-γ, TNF-α and MIP1a in the colitis colon)." (PMID 29872077, 2018). "Further, although mice treated with IL-1β neutralising antibodies display reduced DSS inflammation and expression of IL-6 mRNA transcripts, TNF levels are unaltered, indicating that IL-1β may play a more dominant role in promoting DSS colitis than TNF." (PMID 30542349, 2018). "In this study, we showed that treatment with SH significantly and dose-dependently decreased the plasma levels of IL-6, IL-1β and TNF-a, suggesting that SH may ameliorate colitis through alleviating inflammation." (PMID 30289941, 2018). "After combining this evidence, we hypothesized that TRYP exerted its protecting effect against DSS induced colitis via regulating the TNF-α/NF-κB and IL-6/STAT3 signaling pathways." (PMID 29724065, 2018). "Moreover, the levels of pro-inflammatory cytokines IL-β, IL-6 and TNF-αare increased in dextran sulfate sodium (DSS)-induced colitis in mice." (PMID 29724065, 2018). "Further analysis demonstrated that IL‐35 recombinant protein may regulate inflammation through promoting the secretion of IL‐10 and inhibiting the expression of pro‐inflammatory cytokines such as IL‐6, TNF‐α and IL‐17 in acute colitis model." (PMID 29193791, 2018).
colitis (continued). "However, after treatment with sulfasalazine and TRYP, the levels of IL-6 and TNF-α decreased greatly comparing with the colitis group, while the levels of IL-1β and IL-10 changed insignificantly." (PMID 29724065, 2018). "Moreover, fortunellin (5 or 80 mg/kg) reversed the excessive pro-inflammatory cytokine (TNF-α, IL-1β, and IL-6) profiles and MPO activity in the TNBS-induced colitis model." (PMID 29472916, 2018). "Our in vitro experiments suggest that intestinal M2 macrophages express CCL-20 in colitis via exposure to commensal antigens such as LPS and not as a consequence of direct IL-6-activated transcriptional traits." (PMID 29695802, 2018). "To test whether blocking these pro-inflammatory cytokines can ameliorate colitis in mice, we examined the levels of TNF-α, IL-1β and IL-6 in the inflamed colonic tissue using ELISA." (PMID 29495327, 2018). "IL-6, CSF3, TNF-α, and IL-17 were also induced in the colon of DSS-treated WT mice compared to untreated animals; the levels of induction were comparable to those observed in C. rodentium colitis." (PMID 29922289, 2018). "The serum IL-6 and TNF-α levels were greater in pAdipoR1-DSS mice with colitis." (PMID 29540173, 2018). "TNF-α, IL-6, and IFN-γ are the main inflammatory mediators in murine colitis models." (PMID 30289911, 2018). "WT mice with acute colitis had increased serum levels of IL-6 compared to WT mice, but the serum level of TNF-α was not different." (PMID 29540173, 2018). "In the mouse model, oral administration of KM1608 significantly improved DSS-induced colitis symptoms, such as disease activity index (DAI), colon length, and colon weight, as well as suppressed the expression of IL-6, TNF-α, and myeloperoxidase (MPO) in the DSS-induced colitis tissues." (PMID 30126158, 2018). "Interestingly, PSMP increases were observed in the initial stage in the DSS-induced colitis model; at this time, CCL2, IL-6 and TNF-α were still expressed at low level." (PMID 28698550, 2017). "Exercise significantly decreased macroscopic and microscopic colitis, substantially increased CBF and attenuated the plasma TNF-α, IL-6, MCP-1, IL-1β and leptin levels while raising the plasma irisin and the plasma and WAT concentrations of adiponectin in HFD mice (p < 0.05)." (PMID 28425943, 2017). "Decarine reduced IL-6 and IL-8 production in TNF-α+IL-1β-induced Caco-2 cells, which indicated anti-inflammatory activity on human colon cells and justified the use of Maqian as a remedy for colitis." (PMID 28383530, 2017). "While cibinetide did not affect erythropoiesis, it reduced the influx of myeloid cells into the lamina propria and inhibited the local production and systemic availability of TNF, IL-6, IL12/IL-23, myeloid derived chemokines and nitric oxide (NO) in mice suffering from DSS colitis." (PMID 29026145, 2017). "We found that the levels of active IL-1β and IL-18, which are induced by the inflammasome, but not IL-6 and TNF-α, were associated with increased FLC and inflammatory damage in colitis tissues or tumor formation in AOM/ DSS-induced CAC." (PMID 28701727, 2017). "The oral intake of a multi-fiber mix (MF) can reduce intestinal inflammation in a DSS-stimulated colitis model through the reduction of TNF-α, IL-6 and the increase of IL-10 expression, and it also increases the number of Treg cells in the mesenteric lymph nodes." (PMID 28654020, 2017). "To investigate how F991 reduced DSS-induced colitis, we used ELISA to analyze the levels of proinflammatory cytokines, including IL-6 and TNF-α, and the levels of the anti-inflammatory cytokine IL-10 in cultured supernatant from DSS-colitis tissues after F991 treatment on the 2nd, 4th, 6th days." (PMID 28701727, 2017). "In addition, RA resulted in the reduction of the inflammatory-related cytokines, such as IL-6, IL-1β, and IL-22, and protein levels of COX-2 and iNOS in mice with DSS-induced colitis." (PMID 28383063, 2017).
colitis (continued). "In particular, treatment with two specific MALT1 inhibitors, MI-2 and mepazine, dose-dependently attenuated the symptoms of colitis in mice through a decrease in protein and mRNA levels of colonic TNF, IL-1β, IL-6, IL-18, IL-17A, and IFN-γ pro-inflammatory cytokines." (PMID 28179906, 2017). "In addition, oroxylin A down-regulated the production of NF-κB downstream targets, including TNF-α and IL-6, in DSS-induced colitis mice." (PMID 28938606, 2017). "Levels of TNF-α, IL-4 and IL-6 mRNA were significantly increased in the DSS model group compared with the healthy control group, indicating that DSS significantly increased intestinal inflammation in the DSS-induced colitis mouse model." (PMID 29162986, 2017). "Significant reduction of IL-6 by CHST15 siRNA may result, at least in part, in the anti-inflammatory activity during acute DSS colitis." (PMID 27410685, 2016). "Moreover, the M2-BMDM recipient mice possessed less IL-6, TNF-α, and IL-1β in the serum than the colitis-only control mice." (PMID 27094081, 2016). "Because TNBS-induced colitis leads to marked inflammation in a pattern that is similar to that described for CD, the levels of the proinflammatory cytokines IL-12, IFN-γ, TNF-α, IL-6 and IL-17A were analysed." (PMID 27576902, 2016). "In mouse models, IL-6 levels do not decrease during the transition from colitis to tumor development, but instead increase as dysplasia progresses to tumors." (PMID 26998523, 2016). "Mice succumbed to colitis without adrenals with a higher clinical score and augmented systemic levels of IL-6 and lower LPS." (PMID 27403034, 2016). "While 5-HT alone did not induce colitis, high-dose 5-HT significantly increased the levels of proinflammatory cytokine IL-6 and chemokine IL-8 mRNA in the colons." (PMID 27478308, 2016). "Consistent with alleviated colitis in REGγ−/− mice, ELISA analysis of colonic explants revealed less production of pro-inflammatory cytokines and chemokines including KC, MIP2α, CXCL5, IL-1β, IL-6 and TNFα in REGγ−/− mice than in WT counterparts." (PMID 26899380, 2016). "Additionally, MK2−/− mice are highly resistant to experimental colitis due to reduced IL-6 and TNF-α production, while IL-10 is later critical for taming colitis." (PMID 26998523, 2016). "In the present study, CaA could significantly reverse the increase of IL-6, TNFα and IFNγ in DSS colitis mice." (PMID 27177331, 2016). "Interestingly, the expression of IL-6, TACE and phospho-Stat3 in CAC mucosa was higher than those in the colitis mucosa." (PMID 27350830, 2016). "In the present study, PI3K and p-Akt proteins were activated in the colonic mucosa from colitis rats without treatment; in the meantime, the levels of IL-2, IL-6, IL-17, and IL-23 were increased, and the expressions of HSP70 and TGF-β were decreased." (PMID 26273312, 2015). "Furthermore, GL-V9 successfully prevented colitis by inhibiting the elevated levels of IL-1β, IL-6 and TNF-α in serum and the high-production of IL-1β, IL-6, TNF-α, MIP-1α and IFN-γ in colons." (PMID 26327408, 2015). "However, in TNBS colitis rats fed with HFD, the plasma levels of irisin and IL-6 were significantly decreased (P < 0.05) as compared with those fed LFD." (PMID 25684862, 2015). "Lamina propria macrophages of EPRAP-deficient mice exhibited marked increases in the mRNAs corresponding to TNF-α, IL-1β, IL-6, CXCL1, and MCP-1 relative to those of WT mice, indicating that EPRAP contributes critically to inhibiting macrophage activation and colonic inflammation." (PMID 26439841, 2015). "Antibodies against IL6 reduced colitis in TRUC mice without significantly affecting the structure of their intestinal microbiota." (PMID 25917784, 2015). "Specifically, mice with proximally spread, but not distally contained, colitis have increased IL-1β, IL-6, IL-17, TNFα, and IFNγ combined with decreased IL-10 in the distal colon." (PMID 26121642, 2015).
colitis (continued). "Additionally, ELISA showed that the serum levels of IFN-γ, TNF-α, IL-12, IL-6, and IL-1β were down-regulated in a TNBS model of colitis." (PMID 26561804, 2015). "In this study, we mainly focused on the regulation of ID on proinflammatory cytokines but not Th2 cytokines, since it has been reported that the inhibitory effect of ID on DSS-induced colitis is due to the reduction of proinflammatory cytokines including TNF-α and IL-6 in previous study." (PMID 26104582, 2015). "IBD and DSS induced colitis are characterized by elevated levels of proinflammatory cytokines including IFN-γ, TNF-α and IL-6, and also increased NO production, which contribute to the destruction of the epithelium, ulceration of the intestinal mucosa, erosion and infiltration of inflammatory cells." (PMID 25844068, 2015). "Instead, the accumulation of IFNγ+, IL-6+ and IL-17A+ IEL cells in prolapsed CD4cre:PP4f/f mice may only occur during the latter phase of colitis pathogenesis." (PMID 24904742, 2014). "Even though this suggests that IL-6 plays a negative role in colitis, animal models of colitis induced by DSS have shown contradictory results." (PMID 24993179, 2014). "This DSS colitis switches from a Th1-Th17-mediated acute inflammation with increased levels of TNF-α, IL-6 and IL-17, to a predominant Th2-mediated inflammatory response that shows a decrease in TNF-α, IL-6 and IL-17 while increasing levels of anti-inflammatory cytokines IL-4 and IL-10." (PMID 25106058, 2014). "In addition, the mRNA expression of several cytokine/chemokine (IL-6, CXCL1, CCL11, and IL-1β) genes was low in Eng+/− mice at days 18–23 of colitis." (PMID 25114380, 2014). "Compared with the TNBS model group, the DAI scoring, plasma and colonic mucosa Hcy levels, MPO activity and contents of MDA, IL-1β, IL-6, TNF-α, MMP-2, MMP-9 in colon and EB in small intestine were significantly increased in the TNBS-induced colitis rats with simultaneous Hcy injection (P < 0.01)." (PMID 24787389, 2014). "Preadipocytes, which are specific to the SVF, are known to express high levels of IL-6 in response to LPS and may represent the major cell type responsible for MAT cytokine expression during acute colitis." (PMID 24386254, 2013). "Colitis-induced upregulation of TNF-α, IL-1β, and IL-6 occurred predominantly in the SVF." (PMID 24386254, 2013). "IL-6 and TNF-α are key mediators in a number of experimental colitis models." (PMID 24223664, 2013). "We found that anti-TNF-α, antibiotics, anti-IL-12p40, anti-α4β7 integrin, CTLA4-Ig, and anti-IL-6 effectively prevented onset of colitis, whereas TNFR-Fc and cyclosporine did not." (PMID 22536543, 2012). "Furthermore, increased production of pro-inflammatory cytokines, including interferon (IFN)- γ, TNF-α, IL-1, IL-6, IL-12, and IL-17, has been found in the colon of mice with DSS-induced colitis." (PMID 22479648, 2012). "Collectively, we found that CTLA4-Ig, anti-IL-12p40 mAb, and antibiotics prevented onset of colitis and cured established disease, while anti-TNF-α mAb, anti-IL-6 mAb, and anti-α4β7 mAb prevented onset of colitis but did not reverse established disease." (PMID 22536543, 2012). "In addition, the overproduction of numerous inflammatory mediators such as IL-1β, IL-6, tumor necrosis factor (TNF)-α, as found in cultures of mice with colitis." (PMID 22400037, 2012). "IL-6 and S100A9 expression, signal transducer and activator of transcription 3 (STAT3) phosphorylation, and infiltration of immune cells were analyzed in mice with dextran sulfate sodium (DSS)-induced colitis." (PMID 22962574, 2012). "Using the SCID adoptive transfer colitis model, we have evaluated the effect of currently used IBD drugs and IBD drug candidates, that is, anti-TNF-α, TNFR-Fc, anti-IL-12p40, anti-IL-6, CTLA4-Ig, anti-α4β7 integrin, enrofloxacin/metronidazole, and cyclosporine." (PMID 22536543, 2012).